CCR3 (C-C motif chemokine receptor 3)
Diseases named in the same sentence as CCR3 in open-access papers (continued):
Sharing a sentence is not in itself a finding about the gene and the disease.
infection (continued). "Given the rapid (within 1 hr) increase of neutrophil CCR3 surface expression upon STm infection, we hypothesized that CCR3, akin to CR1, may be stored intracellularly in neutrophils, consistent with reports of intracellular CCR3 in eosinophils." (PMID 39193987, 2024). "As expected, we found that CCL11 together with CCL2, CCL3, and the receptors CCR2, CCR3, and CCR5 were all upregulated in newly-weaned hamster brain tissues after Delta variant infection at 2, 4, and 7 dpi, of which CCL11 and CCR2 were significantly higher at 4 dpi." (PMID 37122119, 2023). "It is therefore possible that longer-term primary infections might resolve the relative roles of IL-4Rα, IL-5, and CCR3 in eosinophil-mediated control of circulating mf." (PMID 32571840, 2020). "Our data demonstrate multiplicity of Th2-cytokine control of eosinophil tissue recruitment during chronic filarial infection and that IL-4R–independent/IL-5– and CCR3-dependent pathways are sufficient to control filarial adult infection via an eosinophil-dependent effector response prior to patency." (PMID 32571840, 2020). "Further, CCR3-deficiency did not affect initial Mφ expansions post-infection or their chronic maintenance +35dpi to +84dpi." (PMID 29547639, 2018). "At a population level, CCR5 usage by R5 C-HIV Envs was strongly linked to usage of FPRL1, CCR3 and CCR8 as alternative coreceptors, with the linkages to FPRL1 and CCR3 usage becoming statistically more robust as infection progressed from chronic to advanced stages of disease." (PMID 24041034, 2013). "Comparison of WT and MUT demonstrated significantly different patterns of host response at early time points of infection (15 minutes, 30 minutes and one hour) within phosphatidylinositol, CCR3, Wnt, and TGF-β signaling pathways and the regulation of actin cytoskeleton pathway." (PMID 22096503, 2011). "In the current study, we explored the long-term consequences of IL-4Rα deficiency and degree of eosinophil recruitment on B. malayi filarial parasitism using a typically nonpermissive BALB/c mouse model of infection and additional IL-5 and CCR3 compound deficiencies." (PMID 32571840, 2020). "Because distinct immune responses are triggered against different life cycle stages of filarial parasites, we scrutinized whether either IL-4R–dependent or IL-4R–independent/CCR3- or IL-5–dependent immunity was also operating at the level of stage-specific mf infections." (PMID 32571840, 2020). "Interestingly, the CCR3 gene is also differentially expressed between the 2 infection conditions." (PMID 23469251, 2013). "Our study identified upregulation of both PRG3 and CCR3 in FUN, while in PYL PRG3 was upregulated only at 3–5 dpi, suggesting a differential and physiological role of FUN and PYL during the infection." (PMID 40076885, 2025). "Both receptors were present on a small subset of bone marrow neutrophils (~4% CCR3, ~0.2% CCR10) and blood neutrophils (~5% CCR3, ~1% CCR10) during infection." (PMID 39193987, 2024). "Furthermore, the chemokine receptor CCR3 usually mediates the recruitment of innate immune cells, and BALB/c mice lacking CCR3 exhibit higher susceptibility to human-specific Loa loa castellani, indicating the critical role of innate immunity in the anti-infection abilities of L. sigmodontis." (PMID 37637465, 2023). "Th2 cells express both CCR3 and CCR4 receptors that bind chemokines to direct their migration to the site of injury or infection." (PMID 32010048, 2019). "Increased expression of Ccl24, CCR3, IL4 and Pdgfc in C57BL/6J mice compared to that in Trim55-/- mice at day four post infection correlates with increased inflammatory cell recruitment and binding to extracellular matrix proteins." (PMID 26452100, 2015). "Contrary to the pattern of Th1-type response gene expression, 5 of the 14 Th2 type response genes (IL5, CCL11, CCR3, IL1RA and GATA3) were significantly downregulated at 2, 4, 8 and 12 weeks post-infection." (PMID 23448601, 2013).
infection (continued). "At 15 minutes post-infection, Phosphatidylinositol Signaling System, Regulation of Actin Cytoskeleton, Tight Junction, Wnt Signaling, TGF-β Signaling, BRC Signaling, and CCR3 Signaling in Eosinophils pathways were down-regulated." (PMID 22096503, 2011). "Comparing the mock and SARS-CoV infected adult DCs, there was moderate induction of CCR-1, CCR-3, CCR-5 and CCR-7 at both 3 h and 9 h post infection but only that observed for CCR-1 and CCR-5 reached statistical significance." (PMID 19505311, 2009). "In addition to CCR10, CCL28 also binds CC chemokine receptor 3 (CCR3), which is expressed on CD4+ T cells in nasal mucosa, as well as eosinophils, basophils, and neutrophils following infection." (PMID 40975172, 2025). "Although the majority of eosinophils (CD11b+ SiglecF+ Side-scatterHigh) detected in the gut and blood expressed CCR3, we found no alteration in their numbers in the gut, blood, or bone marrow in homeostasis or during STm infection." (PMID 39193987, 2024). "During infection with C. violaceum, however, Ccr3 is not expressed at any timepoint, further supporting that eosinophils are not involved in the granuloma response to C. violaceum." (PMID 38352492, 2024). "Bayesian network modeling identified effects of infection on several interrelated signaling pathways including MAPK, Phosphatidylinositol, mTOR, Calcium, Toll-like Receptor, CCR3, Wnt, TGF-β, and Regulation of Actin Cytoskeleton and Apoptosis that were used to model of host-pathogen interactions." (PMID 22096503, 2011). "The results of this study demonstrate that the increase in production of RANTES follows the course of P. yoelii 17XL malaria infection, thus RANTES and its receptors CCR1, CCR3 and CCR5 were detected at their highest levels at day six and day eight post-infection." (PMID 16359553, 2005). "However, in the CNS, CCR3 and CCR5 are also required to promote efficient infection." (PMID 31614895, 2019). "Interestingly CXCR3 ligands have been postulated to be antagonists for CCR3, and the expression of both sets of chemokines may reflect a high degree of dysregulation during HPIs and the recruitment of multiple immune cell types that may not normally co-localize during a controlled infection." (PMID 22189154, 2011).
cancer (49 papers, 2009 to 2025). A tumor composed of atypical neoplastic, often pleomorphic cells that invade other tissues. "CCR3 is a novel receptor associated with development, progression, and aggressiveness of several types of cancer." (PMID 27086913, 2016). "In addition, there was a trend toward an association between high CCR3 mRNA levels and reduced cancer‐specific survival (p = 0.055)." (PMID 40896244, 2025). "Thus, CCR3 is implicated in cancer metastasis and inflammatory conditions." (PMID 34490352, 2021). "To date, data in the literature indicate the important role of CCR3 in disorders such as inflammation, asthma, allergies, and cancer and, recently, in neuropathy." (PMID 38612597, 2024). "Activated CCL28 binds to CCR3 and CCR10, and can control the targeted migration of TILs, Tregs, and cancer‐associated stellate cells." (PMID 36952458, 2023). "The diagrammatic illustrations of three sequential steps demonstrate our proposal to explain the major mechanism of how CAF-induced CCL11/CCR3 signaling in TME contributes to cancer behavior." (PMID 35804913, 2022). "Chemokines (CCR1, CCR2, CCR3, CCR4, CCR5, CCR6, CCR7, and CCR8) and receptor genes (CXCL1-17, CCL1-14, CCL16-26) were positively associated with necroptosis levels in various cancers." (PMID 36170029, 2022). "In our result, we verified the existence of the main corresponding receptor of CCL11, CCR3, that is directly involved in signaling transduction and cancer progression by confocal microscopy and immunohistochemistry." (PMID 35804913, 2022). "Although these results suggest that CCR3 favors the homing of PCa cells to bones, we cannot formerly exclude that cancer cells began expressing CCR3 once they have reached the bone in response to the bone environment." (PMID 33671469, 2021). "The over-expression of CCR3 was demonstrated in bone metastasis vs. primary tumors using the cancer microarray database, Oncomine, and at the protein levels in bone vs. visceral metastasis by immunohistochemistry." (PMID 33671469, 2021). "The majority of published papers indicate that eotaxins and their receptor (CCR3) show high expression in cancer tissues when compared to healthy controls." (PMID 32481530, 2020). "HPV18E6 did deregulate cancer pathways, CCR3 signaling in eosinophil and IL8 signaling and the COPD pathway." (PMID 29164058, 2017). "It warrants further investigation regarding the precise mechanism of CCR3 modulating luminal-like cancer." (PMID 27086913, 2016). "Using combined in vitro and in vivo approaches, we demonstrate here that the ability of PPAT to attract cancer cells away from the prostate gland is dependent on an original CCR3/CCL7 axis." (PMID 26756352, 2016). "We then demonstrated in vitro that both CCL11 and its receptor, CCR3, were overexpressed and promoted the proliferation, migration and invasion of cancer cells." (PMID 27119233, 2016). "Additionally, mature adipocytes can secrete CC-chemokine ligand 7 (CCL7), which directly promotes cancer cell migration by interacting with the CC-chemokine receptor 3 (CCR3) on PCa cells." (PMID 40703555, 2025). "Moreover, it was shown that CCR3 plays an important role in the pathogenesis of osteoarthritis, allergic asthma, and cancer in patients." (PMID 38612597, 2024). "For precision medicine-based clinical practice, modulating the TME by targeting the CCL11/CCR3 signaling circuit may attenuate the aggressiveness of cancer cells and offer a novel therapeutic strategy to improve the prognosis in patients with HNC." (PMID 35804913, 2022). "As the downstream of CCL24, CC chemokine receptor 3 (CCR3) was also involved in many cancer." (PMID 28042950, 2017). "Of note, high CCR3 expression was more prevalent in luminal-like cases, indicating CCR3 might be involved in luminal-like cancer development." (PMID 27086913, 2016). "Moreover, our data demonstrated that both CCL11 and CCR3 promote the proliferation, migration, and invasion of cancer cells." (PMID 27119233, 2016).
cancer (continued). "We then examined the expression of CCL11 in several cell lines and human GBM samples, and investigated whether CCL11 and CCR3 contributed to the proliferation, migration and invasion of cancer cells in vitro." (PMID 27119233, 2016). "Compared with NHA, the levels of both CCL11 and CCR3 were increased in cancer cells." (PMID 27119233, 2016). "The majority of the genes identified here, including but not limited to CCR1, CCR2, CCR3, ENA78, GPCR, GRO1, GRO2/GRO3, IP10, IL-8, NAP-2, PF-4 have been recently shown to associate with the progression of various types of cancer." (PMID 22347499, 2012). "Therefore, CCR3 and its ligands are therapeutic targets for allergic diseases and cancers." (PMID 36546900, 2022). "Certain receptors display consistent co-regulation patterns across cancer tissues and subtypes even if bound to multiple ligands (e.g., CXCR3, CCR3, CCR5)." (PMID 38723607, 2024). "Other chemokine receptors, such as CCR1, CCR3, or CCR5, are significantly co-upregulated across different cancer subtypes." (PMID 38723607, 2024). "Concentrations of CCR3, CEA, and CRP in the total cancer group were statistically significantly higher when compared to the control group (in all cases p < 0.05)." (PMID 34204490, 2021). "It is reported that CCR1, CCR2, CCR3 and CCR5 are involved in CCL7‐mediated macrophage migration and contribute to various inflammatory diseases and cancer." (PMID 34189838, 2021). "CCL5 action is mediated through its receptors, C-C chemokine receptor (CCR) 1, CCR3 and CCR5, and carcinoma cells have different expression patterns of these chemokine receptors." (PMID 33671956, 2021). "If the cancer cell stops in the bone, CCL15, produced by the cancer cell, acts chemotactically on osteoclast precursors and osteoclasts, probably via CCR1 and CCR3." (PMID 33182504, 2020). "Our survival analysis revealed that high expression of CCR3, CCR4, and CCR10 is associated with poor cancer‐specific survival in FL‐patients, a finding that has not been reported previously." (PMID 40896244, 2025). "CCL5 receptors include CCR1, CCR3 and CCR5, while in cancer research CCR5 is the main receptor." (PMID 29088737, 2017). "An apparent trend towards lower chemokine receptor expression by T lymphocytes from carcinoma tissue was observed for the receptors CCR3 and CX3CR1, whereas CXCR5 was not expressed at all by T lymphocytes from carcinoma tissue." (PMID 29020986, 2017). "We found that cancer cells themselves could produce CCL11 and overexpress CCR3, indicating the activation of CCL11-CCR3 autocrine signaling in GBM." (PMID 27119233, 2016). "In cancer, CCL11 and CCR3 facilitate proliferation, migration, and invasion of cancer cells." (PMID 27119233, 2016). "Tumors with high expression of CCR3 were more likely to be luminal-like rather than TNBC or HER2-enriched cancers." (PMID 27086913, 2016). "Indeed, there were significantly higher frequencies of CCR3+ NK cells in the circulation of OAC patients relative to non-cancer controls; non-cancer versus OAC (2.983% vs. 11.00%, p = 0.02)." (PMID 38369570, 2024). "Furthermore, we also studied whether CC chemokine receptor 3 (CCR3), the main corresponding receptor of CCL11, is directly involved in signal transduction resulting in cancer progression." (PMID 35804913, 2022). "CCL11 has also been proposed as a biomarker in different types of cancers with however still little evidence that CCL11 or CCR3 expression may serve as a prognostic factor in cancer." (PMID 33608009, 2021). "Silencing CCR3 also weakened the invasion ability of cancer cells, and it could not be restored by CCL11 add back." (PMID 27119233, 2016). "Moreover, we demonstrated that higher intratumoral mRNA expression of CCR3 reduced the risk for cancer relapse in luminal-like disease but not in TNBC and HER2-enriched cancers." (PMID 27086913, 2016).
cancer (continued). "In addition, via binding to CCR3, CCL7 overexpression activates the ERK/JNK signaling pathway that converges on the downstream pathways of the MAPK cascade, thereby participating in the epithelial-mesenchymal transition (EMT) process that is sufficient to strengthen cancer metastasis capabilities." (PMID 29915688, 2018). "The results revealed that none of the CCL5, CCR1, CCR3 and CCR5 was expressed in the ovarian paracancerous tissues, whereas all these molecules were expressed in both primary cancer tissues and metastatic tissues." (PMID 25788271, 2015).
inflammation (6 papers, 2010 to 2024). Aberrant reaction of the microcirculation characterized by movement of fluid and leukocytes from the blood into extravascular tissues. "In mouse models of food allergen-induced GI eosinophilic inflammation, blocking expression of CCR3 significantly reduced the severity of diarrhea, eosinophilic inflammation, and mucosal injury." (PMID 30227886, 2018). "A specific area in which it may be of interest to explore effects of anti-eosinophil active drugs, notably CCR3-antagonists, is the interaction between allergic/eosinophilic inflammation and the common cold." (PMID 20144207, 2010). "The number ofCD45+CCR3+SSChigh granulocytes,representing mature eosinophils, was significantly increased in the lung tissueafter OVA exposure, compared to control PBS exposure, confirming that a model ofallergic airway inflammation had been established." (PMID 21625544, 2011).
neurodegenerative disease (3 papers, 2016 to 2022). A disorder of the central nervous system characterized by gradual and progressive loss of neural tissue and neurologic function. "Understanding how CCR3 contributes to neuronal loss and further investigation into the potential neuroprotective actions of CCR3 inhibition may reveal new therapeutic opportunities for treatment of ischemic injury or neurodegenerative diseases." (PMID 27822494, 2016).
infectious disease (2 papers, 2012 to 2017). A disorder directly resulting from the presence and activity of a microbial, viral, or parasitic agent in humans. "Several inflammatory conditions and infectious diseases also comprise the selective eosinophil chemotaxis and transendothelial migration mediated by the CC-chemokines eotaxin-1, eotaxin-2 and eotaxin-3 (CCL11, CCL24, and CCL26, respectively) via the eotaxin receptor CCR3." (PMID 29322036, 2017).
CCR3 also shares sentences with these, for which no sentence is quoted: Allergy (7 papers); chronic bronchitis (3); oral squamous cell carcinoma (3); eosinophilic esophagitis (2); Hodgkins lymphoma (2); neovascular age-related macular degeneration (2); Parkinson disease (2); prostate (2); psoriasis (2); type 2 diabetes (2); Airway obstruction (1); alveolitis (1); autoimmune PAP (1); bacterial infections (1); bacterial meningitis (1); Behcet disease (1); brain injury (1); bronchiectasis (1); cardiac disease (1); cardiac hypertrophy (1); Cataplexy (1); cervical cancer (1); chronic lung disease (1); chronic obstructive pulmonary disease (1); chronic rhinosinusitis (1); clear cell renal cell carcinoma (1); colorectal tumors (1); coronary artery disease (1); Crohn disease (1); cystic fibrosis (1).
A further 36 diseases each share a sentence with CCR3 in 1 paper.